BMPR1B (bone morphogenetic protein receptor type 1B)
Diseases named in the same sentence as BMPR1B in open-access papers (continued):
Sharing a sentence is not in itself a finding about the gene and the disease.
myeloma (3 papers, 2015 to 2019). "In summary, in bone-lining stromal progenitors, we found BMP pathway members, particularly Bmpr1b, to be enriched in myeloma-bearing mice." (PMID 31586071, 2019).
osteoporosis (3 papers, 2012 to 2025). A condition of reduced bone mass, with decreased cortical thickness and a decrease in the number and size of the trabeculae of cancellous bone (but normal chemical composition), resulting in increased fracture incidence. "As skeletal development or bone formation activity, the markers of osteogenic differentiation of BMSCs, such as RUNX2, COL1a2, and BMPR1B, were decreased in the osteoporosis group." (PMID 27171263, 2016). "To date, the role of LINC00657 in osteoporosis is less understood and only one report demonstrated its proosteogenic role in BMMSC via the miR-144-3p/BMPR1B axis, which is consistent with our results to some extent." (PMID 40873948, 2025).
ovarian carcinoma (3 papers, 2013 to 2022). A malignant neoplasm originating from the surface ovarian epithelium. "Recent studies indicate a tumor suppressor role for BMPR1B in ovarian cancer." (PMID 24339876, 2013).
pulmonary hypertension (3 papers, 2017 to 2025). Increased pressure within the pulmonary circulation due to lung or heart disorder. "Subsequent 14 gene pulmonary arterial hypertension panel revealed a pathogenic deletion of the entire coding sequence of GDF2 as well as a VUS in bone morphogenetic protein receptor type 1B (BMPR1B)." (PMID 40429357, 2025). "BMPR1B emerged as a crucial mediator of BMP2 signaling, regulating pulmonary artery smooth muscle proliferation to mitigate high-altitude pulmonary hypertension." (PMID 41153449, 2025).
Acromesomelic dysplasia, Grebe type (2 papers, 2015 to 2019). "Previously, GDF5 mutations have been shown to constitute the major cause of ACD Grebe and du Pan types, and BMPR1B mutations had been identified in single families with Grebe syndrome and a Grebe dysplasia-like phenotype with genital anomalies." (PMID 26105076, 2015). "Acromesomelic dysplasia Grebe type (AMDG, MIM: 200700) 112 and Demirhan type (AMDD, MIM: 609441) 113 are associated with biallelic loss of activity mutations in BMPR1B (encoding the BMP type I receptor ALK6)." (PMID 30246251, 2019).
brachydactyli type A2 (2 papers, 2009 to 2023). "Conversely, the very highly significant (P < 0.001) association of BMPR1B with front pastern posture suggested that the roles it plays in the pig may be similar to humans, since the mutations in this gene were associated with brachydactyli type A2." (PMID 19284518, 2009).
clear cell renal cell carcinoma (2 papers, 2021 to 2022). "BMPR1B was up-regulated by the loss of oncogenic miR-1274a, reducing cancer cell proliferation and inducing apoptosis in clear cell renal cell carcinoma." (PMID 36536378, 2022). "High expression levels of miR-1274a have been demonstrated in clear cell renal cell carcinoma (ccRCC) compared with adjacent normal cells, which further induced cell apoptosis through the regulation of BMPR1B expression." (PMID 34660637, 2021).
coloboma (2 papers, 2022 to 2023). An abnormality in which a part of a structure in one or both eyes is missing. "Novel pathogenic variants in ANK3, BMPR1B, PDGFRA, and CDH4 were identified in 8 unrelated coloboma families." (PMID 35034853, 2022). "Knockdown of ank3, bmpr1b, and pdgfaa revealed a coloboma and/or microphthalmia phenotype." (PMID 35034853, 2022). "Among these were the known human MAC genes TENM3, SMOC1, PAX2, ALDH1A3, and BMPR1B, in addition to NID1, VAX1, and NTN1, which have been previously identified as MAC or coloboma candidates based on animal studies." (PMID 36830662, 2023).
holoprosencephaly (2 papers, 2008 to 2023). Holoprosencephaly (HPE) is a complex brain malformation resulting from incomplete cleavage of the prosencephalon, occurring between the 18th and 28th day of gestation, and affecting both the forebrain and face, which results in neurological manifestations and facial anomalies of variable severity. "Genetic studies performed on mouse models showed that double knockout of Bmpr1A and Bmpr1B leads to the development of holoprosencephaly." (PMID 37284286, 2023). "Genetic analysis based on the double mutant of Bmpr1A and Bmpr1B showed the existence of two kinds of holoprosencephaly." (PMID 37284286, 2023).
infertile (2 papers, 2020 to 2022). "BMPR1B defects in mice have been shown to cause infertility, and high expression of BMPR1B in ovaries has been related to highly prolific sheep and goats." (PMID 36295085, 2022). "BMPR1B has been found to mediate the AMH response in ovine granulosa cells, and BMPR1B-deficient mice are infertile and suffer from a variety of functional defects in the ovary." (PMID 32574161, 2020).
leukemia (2 papers, 2021 to 2023). A malignant (clonal) hematologic disorder, involving hematopoietic stem cells and characterized by the presence of primitive or atypical myeloid or lymphoid cells in the bone marrow and the blood. "At diagnosis of leukemia and breast cancer, BMPR1b was evidenced as an important transducer of BMP signals, acting as an amplifier of the normal SC response to BMP." (PMID 35047500, 2021). "A study indicated that BMPR1B, Stat3, and BMP4-niche signaling pathways regulate leukemia remission." (PMID 37373155, 2023). "Alteration of BMP receptor type 1b (BMPR1b) expression at the HSC surface is induced by the expression of BCR-ABL and these molecular changes led to altered responses of leukemia cells to BMP2 and BMP4 as compared to normal bone marrow cells." (PMID 35047500, 2021).
Obesity (2 papers, 2020 to 2023). Accumulation of substantial excess body fat. "Still, whether through the regulation of BMSCs differentiation (FMN1 and BMPR1B), glucose metabolism (MAGI2), or initiation of the inflammatory process (SKAP2), these genes could be relevant to the development of obesity." (PMID 33003475, 2020).
Osteopenia (2 papers, 2016 to 2020). Osteopenia is a term to define bone density that is not normal but also not as low as osteoporosis. "We found that deletion of Bmpr1b leads to osteopenia in 8-week-old male mice, which is likely due to the compromised osteogenic differentiation of bone marrow mesenchymal progenitors, but not that of pre-osteoblasts." (PMID 27048979, 2016). "Our present results demonstrated that deletion of Bmpr1b leads to osteopenia in 8-week-old male mice." (PMID 27048979, 2016). "We found that deletion of Bmpr1b resulted in osteopenia in 8-week-old male mice, and the phenotype was transient and gender specific." (PMID 27048979, 2016). "Global Bmpr1b knockout resulted in a transient and gender-specific osteopenia in 8-week-old male Bmpr1b null mice, however, in vivo bone turnover analysis did not detect changes in either bone formation or bone resorption." (PMID 33178699, 2020).
osteosarcoma (2 papers, 2013 to 2016). A usually aggressive malignant bone-forming mesenchymal neoplasm, predominantly affecting adolescents and young adults. "The osteosarcoma cell line U-2 OS showed highest expression of BMPR1A by IHC, which was echoed in RNAseq data from three sarcoma cell lines, where BMPR1A expression far exceeded that of BMPR1B." (PMID 27114889, 2016).
ovarian insufficiency (2 papers, 2022 to 2023). "The Bmpr1b missense mutation can cause cumulus expansion disorder and premature depletion of ovarian follicles, leading to ovarian insufficiency." (PMID 37305038, 2023). "In addition, a series of studies have confirmed that the BMPR1B can affect follicular development, ovulation, and cause ovarian insufficiency." (PMID 35681821, 2022).
prostate carcinoma (2 papers, 2016 to 2023). A carcinoma that arises from epithelial cells of the prostate gland. "Notably, one group of genes with very strong negative correlations (≤-0.9) to radiomic features were found to be associated with the AR signaling genes: KLK2, KLK3, HOMER2, BMPR1B, or belong to validated prostate cancer classifiers: CHRNA2, MT1H, DPP4, MYBPC1." (PMID 27438142, 2016). "However, the finding that BMPR1b and not BMPR1a is elevated in blastic‐like prostate cancer cell lines is compelling." (PMID 36054271, 2023).
acromesomelic dysplasia 3 (1 paper, 2024). "The only finding was a heterozygous variant of unknown significance in BMPR1B (c1460T>A, p.(Val487Asp)), which encodes a bone morphogenic receptor involved in brachydactyly syndromes A1, A2 and D and acromesomelic dysplasia 3 (only the latter being an autosomal recessive condition)." (PMID 38879467, 2024).
Autoimmunity (1 paper, 2022). The occurrence of an immune reaction against the organism's own cells or tissues. "Both NK activation and autoimmunity are linked to BMP signaling, e.g., via an autocrine activation pathway via BMP receptors and BMP ligands in NK cells, which fits our identified target genes BMP1, BMP2, BMP3, BMP7, BMP6, BMPER, BMPR1B, and, most importantly, BMPR2." (PMID 35455956, 2022).
brachydactyly type A1 (1 paper, 2021). A rare, congenital limb malformation characterized by shortened or underdeveloped middle phalanges of all digits, that are sometimes fused with the terminal phalanges. "In addition, BMPR1b mutations were linked to Brachydactyly type A1 characterized by bones hyperplasia, indicating that BMPR1b alterations could affect both the HSCs and MSCs in different physiopathological contexts by affecting their response to BMP4." (PMID 35047500, 2021).
colon cancer (1 paper, 2014). "We only observed marginally significant associations with BMP2 (PARTP = 0.083), BMPR1A (PARTP = 0.053), BMPR1B (PARTP = 0.069) for colon cancer survival." (PMID 25541970, 2014).
colorectal adenocarcinoma (1 paper, 2023). The most common type of colorectal carcinoma. "So, to further investigate the roles of PCTK1 and BMPR1B in CRC, we retrieved a list of co-expression genes from the Colorectal Adenocarcinoma (TCGA, Firehose Legacy) dataset available in cBioPortal." (PMID 37373155, 2023).
COVID-19 (1 paper, 2023). A disease caused by infection with severe acute respiratory syndrome coronavirus 2. "Conversely, the BMP and TGFβ signaling pathways showed specific down-regulation in endothelial cells from COVID-19 hearts, including down-regulation of BMPR1A, BMPR1B, SMAD6, and BMP6." (PMID 37830426, 2023).
germ cell tumor (1 paper, 2013). A benign or malignant, gonadal or extragonadal neoplasm that originates from germ cells. "Recent advances have implicated the KITLG/SPRY4/BAK1 and TGFβ/BMP-signaling (BMPR1B) pathways in germ cell tumor development, which include the control of differentiation, cell proliferation and apoptosis." (PMID 23599692, 2013).
granulosa cell tumor (1 paper, 2016). A slow-growing, malignant tumor, characterize by the presence of granulosa-like cells and Call-Exner bodies, that is almost always found in the ovary. "The expression of Gli genes that encode transcription factor effectors of sonic hedgehog signaling is also upregulated in the granulosa cell tumors of Bmpr1a/Bmpr1b conditional knockout mice." (PMID 27344183, 2016).
Grebe dysplasia (1 paper, 2015). "We show that the homozygous c.91C>T, p.(Arg31Cys) mutation causing du Pan dysplasia leads to a significant loss of BMPR1B function, but to a lesser extent than the previously reported p.Cys53Arg mutation that results in the more severe Grebe dysplasia." (PMID 26105076, 2015).
helminth infections (1 paper, 2021). "The bone morphogenetic protein receptor type 1B (BMPR1) gene on BTA 6 was annotated to the cytokine–cytokine receptor interaction and to the TGF-β signaling pathway, which are involved in the secretion and up- and downregulation of cytokines during helminth infections." (PMID 34440337, 2021).
liposarcoma (1 paper, 2016). A usually painless malignant tumor that arises from adipose tissue. "In summary, we present here evidence that high expression of BMP2 leads to extracellular matrix remodelling and tumour progression in dedifferentiated liposarcomas, only within the context of high BMPR1B expression." (PMID 27114889, 2016).
lymph node metastasis (1 paper, 2021). "Furthermore, BMPR1A, BMPR1B, and BMPR2 were associated with clinical factors, including age, ethnicity, tumor size, and lymph node metastasis." (PMID 34036102, 2021).
lymphoma (1 paper, 2024). A malignant (clonal) proliferation of B- lymphocytes or T- lymphocytes which involves the lymph nodes, bone marrow and/or extranodal sites. "For BMP receptors, the expression of BMPR1B and ACVRL1 was barely detectable in lymphoma cells." (PMID 38229201, 2024).
mastitis (1 paper, 2021). Inflammation of breast tissue during lactation or postpartum due to an obstructed duct or infection. "The BMPR1B gene was described to be involved in immune response to the mastitis pathogen Staphylococcus aureus and is related to the cytokine–cytokine interaction and TGF-ß signaling pathway." (PMID 34440337, 2021).
muscular dystrophy (1 paper, 2020). Muscular dystrophy (MD) refers to a group of more than 30 genetic diseases characterized by progressive weakness and degeneration of the skeletal muscles that control movement. "We found that all the muscular dystrophy models have an upregulation of Mmp10 and Bmpr1b gene expression compared to WT mice." (PMID 31754018, 2020). "This analysis was limited to bone from 7-week-old mice and revealed a 2- to 3.75-fold upregulation of matrix metalloprotease 10 (Mmp10) and bone morphogenetic protein receptor type 1b (Bmpr1b) in all muscular dystrophy models compared to WT mice." (PMID 31754018, 2020). "MMP-10 and BMPR1b were chosen because they were upregulated in all muscular dystrophy mouse models." (PMID 31754018, 2020). "Thus, our findings of increased skeletal Bmpr1b expression in mdx, mdx:Utrn+/− and mdx:Cmah−/− mice are consistent with their use as preclinical muscular dystrophy models." (PMID 31754018, 2020). "Selected genes from this array were validated by immunohistochemistry (IHC) to confirm the presence of IGF-1, BMPR1b and MMP-10 proteins in tibial sections from WT and muscular dystrophy mice." (PMID 31754018, 2020).
polyposis (1 paper, 2018). "We predicted that the protein of FecB (BMPR1B) was also expressed in colonic epithelial cells, and aberrant BMP signaling was associated with polyposis." (PMID 29439449, 2018).
renal fibrosis (1 paper, 2022). A final common manifestation of a wide variety of chronic kidney diseases characterized by glomerulosclerosis and tubulointerstitial fibrosis. "BMPR1B plays a key role in renal signal transduction and protection against renal fibrosis." (PMID 36104709, 2022).
sarcoma (1 paper, 2016). A usually aggressive malignant neoplasm of the soft tissue or bone. "By stratifying the 263 samples represented in the TCGA sarcoma dataset based on the ratio of BMPR1A to BMPR1B mRNA, we were able to define two clear groups." (PMID 27114889, 2016). "We reasoned that as BMPR1A expression is enriched relative to BMPR1B in sarcoma cell lines, BMP2-BMPR1A signalling may be important in progression of this tumour type." (PMID 27114889, 2016). "To discount prognostic influences of BMPR1A, BMPR1B or BMP2 expression individually, we constructed Kaplan-Myer curves for the entire sarcoma dataset and compared patients with the highest and lowest 10% expression of BMPR1A, BMPR1B, BMPR2, BMP2 and BMP7." (PMID 27114889, 2016).
sterility (1 paper, 2025). "The BMPR1B c.746A>G mutation, also known as the FecB (Fecundity Booroola) mutation, demonstrates a classic example of gene dosage effects where heterozygous carriers benefit from increased fertility while homozygous carriers can experience fertility problems or sterility." (PMID 40723346, 2025).
tumor (31 papers, 2011 to 2025). "By analyzing the differential genes in cluster 12, we further found that the average expression level of BMPR1B gene in tumor-derived epithelial cells was higher than that in interface-derived epithelial cells (left)." (PMID 37644609, 2023). "We investigated the functions of a gene BMPR1B whose expression gradually increased in luminal cells from the normal to the interface to the tumor zone." (PMID 37644609, 2023). "The experimental evidence revealed that BMPR1B expression affected tumour growth in ER positive carcinomas." (PMID 37333824, 2023). "As a whole, the average expression level of BMPR1B gradually increased from the normal to the interface to the tumor-derived luminal cells." (PMID 37644609, 2023). "Cell proliferation, wound healing and clone formation experiments explored the function of differentially expressed gene BMPR1B, which were confirmed by tumor models in vivo." (PMID 37644609, 2023). "Several reports using genetically modified mouse models highlight the importance of TGFB superfamily signaling components, such as INHA, SMAD3, SMAD1/5, and BMPR1A/BMPR1B, in sex cord-stromal tumor development." (PMID 29221447, 2017). "BMPR1A expression was globally reduced across all CRC subtypes, but BMPRII expression was retained and BMPR1B expression was upregulated specifically in mesenchymal tumours." (PMID 28299802, 2017). "In the SWI/SNF-mutant cohort, a seven-gene signature comprising CRIM1 (angiogenesis), VEGFC (lymphangiogenesis), BMP7 (tumor microenvironment regulation), NR1D2 (immune modulation), BMPR1B (tumor proliferation), CR2 (B-cell activation), and TAPBPL (antigen presentation) was ultimately retained." (PMID 41438758, 2025). "The expression of BMPR1B gene between tumor and normal zones is consistent with the TCGA database." (PMID 37644609, 2023). "In addition, the average expression level of BMPR1B was higher in both the interface- and tumor-derived epithelial cells in cluster 12 than in all luminal epithelial cells in the normal zone (middle and right)." (PMID 37644609, 2023). "Moreover, suppression of GATA6 induced expression of the Bmp receptor (Bmpr1b) and rendered these tumor cells more sensitive to exogenous Bmp7 stimulation and downstream Smad9 expression." (PMID 32157212, 2020). "We first sought to examine the expression levels of BMPR2, BMPR1A and BMPR1B in NB tumour samples." (PMID 32714600, 2020). "Indeed, BMPR1b was mostly detected in the cytoplasm of both basal and luminal tumor cells and its localization was more diffuse than in healthy tissues." (PMID 27740625, 2017). "Interestingly, although the BMPR1b receptor is primarily localized in the apical membrane of luminal cells in healthy mammoplasties, as well as in the normal adjacent tissue of luminal tumors, we observed by immunohistochemical staining a different cellular localization of BMPR1b in tumor tissues." (PMID 27740625, 2017). "MiR-hsa-125b-5p affects cell proliferation, migration, and invasion by targeting multiple tumor suppressor genes such as CD147 and TPD52, and it participates in cancer progression by targeting STAT3, BMPR1B, VEGFA, SphK1, CDKN2A, and Sema4D." (PMID 41361055, 2025). "We also found that BMPR1B was negatively correlated with PCTK1 in CRC cells, and BMPR1B expression was upregulated in PCTK1-KO cells and xenograft tumor tissues." (PMID 37373155, 2023). "Reduced expression of eight immune‐related genes (IRGs) (NT5E, THRA, RBP1, TLR4, ITGA6, BMPR1B, ITGAV, SSTR1) in tumor strongly predicted better quality of prognosis, both in our patient cohort and in TCGA‐HNSC cohort." (PMID 37392167, 2023).